HOXA13 (homeobox A13)
Diseases named in the same sentence as HOXA13 in open-access papers (continued):
Sharing a sentence is not in itself a finding about the gene and the disease.
preeclampsia (1 paper, 2025). Preeclampsia is a hypertensive disorder of pregnancy that is characterized by new-onset hypertension with proteinuria presenting after 20 weeks of gestation, and depending on mild or severe forms may initially present with severe headache, visual disturbances, and hyperreflexia. "Importantly, hypermethylation of HOXA13 has been confirmed in the placental tissues of individuals with preeclampsia." (PMID 40877960, 2025). "Importantly, hypermethylation of HOXA13 has been observed in the placental tissues of preeclampsia." (PMID 40877960, 2025). "Importantly, hypermethylation of HOXA13 has been existed in the placental tissues of preeclampsia." (PMID 40877960, 2025).
uterine fibroids (1 paper, 2019). "Together, these results support the notion that development of uterine fibroids is, in fact, at least a partial homeotic transformation into a more cervical phenotype, probably by induced expression of HOXA13 in normal myometrial cells." (PMID 31851934, 2019).
viral infection (1 paper, 2024). "In terms of HOXA13 in viral infection or inflammation, HOXA13 participates in inflammation activation." (PMID 38902760, 2024).
cancer (46 papers, 2010 to 2025). A tumor composed of atypical neoplastic, often pleomorphic cells that invade other tissues. "Spearman correlation analysis was performed to evaluate a possible association between hsa-miR-1249-3p and HOXA13 mRNA levels in epithelial and cancer cell lines and pre-cancerous tissues." (PMID 38129477, 2023). "As a member of the HOX gene family, HOXA13 has been specifically implicated as the critical factor of the progression of some cancers." (PMID 35197128, 2022). "HOXA13 is linked to poor prognosis in many cancers and HMOX1 has a role in protecting tumor cells from apoptosis." (PMID 32550915, 2020). "In recent studies, the aberrant role of HOXA13 in cancer is frequently associated with HOTTIP expression, suggesting that their interaction is strongly related to the modulation of tumor evolution and progression." (PMID 31137568, 2019). "HOXA13 is upregulated in more advanced GC stages and associated with cancer cell invasion suggesting it may play an important role in IM transformation to malignancy." (PMID 35448971, 2022). "HOXA13, whose over-expression in UL has previously been described, is also associated with tumor size, microvascular invasion, angiogenesis, Wnt and TGFβ3 pathway in cancer." (PMID 35740301, 2022). "It has been suggested that the HOXA13 protein may be involved in the morphogenesis of cancer cells by causing abnormalities in cell adhesion, which affect the interactions between cancer cells and their extracellular matrix, thus enabling tumor invasion and metastasis." (PMID 37627895, 2023). "On the contrary, there are also some genes, such as HOXB3, HOXD1, HOXC9, and HOXA13, that are highly expressed in some cancers and have better OS (p<0.05)." (PMID 39980564, 2025). "High expression of genes such as HOXB5, HOXC11, HOXA13, HOXD13, HOXA6, and HOXC6 in certain cancers is linked to poor overall survival (OS)." (PMID 39980564, 2025). "HOXA13 upregulation has been shown to be a poor outcome marker in some adult cancers, but the role of HOXA13 overexpression in WT development is not apparent." (PMID 39687897, 2024). "In summary, HOXA13 plays a role as a cancer-promoting gene in NPC and can promote the proliferation, migration, and invasion of NPC HNE1 cells by upregulating Snail and MMP-2." (PMID 37563232, 2023). "HOXA13 was documented as a marker of gut primordial posteriorization and plays a key role in tumorigenesis of variety of cancers." (PMID 37392284, 2023). "Recently, a booming number of studies have demonstrated that aberrant HOXA13 expression correlates with proliferation, metastasis, prognosis and chemoresistance in various types of cancer." (PMID 34094932, 2021). "While the significant role HOXA13 plays in various cancers, the specific mechanism of HOXA13 in GC chemoresistance remains to be further explored." (PMID 34094932, 2021). "Our results showed that multiple cancer-associated pathways were identified in LSCC tissues with high expression of HOXA13, and high expression of HOXA13 in LSCC predicted poor overall survival." (PMID 32296636, 2020). "HOXA13 knockdown significantly restored the epithelial characteristics and reduced the mesenchymal characteristics of the cancer cells via the transforming growth factor (TGF)-β signaling pathway." (PMID 32296636, 2020). "Increasing evidence now indicates that dysregulated expression of HOX genes, including HOXA13, in a variety of cancers is closely related to tumor development and progression." (PMID 31234415, 2019). "Among the potential target genes, HOXA13 was predicted to contain the binding sequence of miR-381, and its upregulation was shown to enhance cancer cell proliferation and invasion." (PMID 30581456, 2018). "The role of HoxA13 in cancer progression has been reported in hepatocarcinogenesis, especially in the liver stem-like cell lines, and in prostatic neoplasia, leukemogenesis, and esophageal squamous cell carcinoma." (PMID 27144338, 2016).
cancer (continued). "We chose five lncRNAs (HOTAIR, HOXA-AS-2, lincRNA—ROR, MALAT1, and ANRIL) and three mRNA Homeobox A13 (HOXA13), SRY-box 2 (SOX2) and POU class 5 homeobox 1 (POU5F1/OCT4) implicated in a range of cancers, including UBC." (PMID 26800519, 2016). "Pathway analysis revealed that a high proportion of the genes that were positively correlated to HOXA13 were enriched in cancer-related pathways, focal adhesion, the Wnt signaling pathway, and the cell cycle." (PMID 26356815, 2015). "In HCC, however, to date, only a few studies implicated lncRNAs, such as MALAT1, HOTAIR, HOTTIP/HOXA13, H19, HULC, MEG3, in the cancer pathogenesis." (PMID 25686840, 2015). "The other HOX genes that are notably upregulated in SK-OV3 cells (but generally not OV-90 cells) have previously been shown to be upregulated in other cancers, including HOXA13, HOXB5, HOXB9 and HOXD9." (PMID 20219106, 2010). "However, some genes exhibit cancer heterogeneity, such as HOXA13, whose high expression has better OS in SKCM and worse OS in KIRC." (PMID 39980564, 2025). "Among these, HOXB7, HOXA13, HOXA10, and HOXC10 have been associated with cancer." (PMID 38761291, 2024). "Also, in LUAD, Homeo box A13 (HOXA13) which is a transcriptional factor augments SLC3A2 expression in increasing cancer progression." (PMID 38705513, 2024). "In summary, our results suggest that HOXA13 plays a role as a cancer-promoting gene in NPC." (PMID 37563232, 2023). "HOXA13 deregulation in cancer has been recently validated by a meta-analysis study." (PMID 31137568, 2019). "Similarly, Hottip is upregulated in several cancers where its expression also correlates with increased Hoxa13." (PMID 28384324, 2017). "Furthermore, we also observed a positive correlation between HOTTIP and HOXA13 expression levels both in cancer cell lines and clinical samples." (PMID 25889214, 2015). "Homeobox (HOX) genes, including HOXA13, are involved in human cancer." (PMID 26356815, 2015). "This difference implies that HOXA13 regulation of cancer cell function may be dependent on the location of HOXA13 protein and that HOXA13 in different subcellular localizations seems to have different functions." (PMID 26356815, 2015). "Thus, HOXA13 may play a role as an oncogene in these cancers." (PMID 37627895, 2023). "HOXA13, a member of the HOX gene family, has been found to function as a cancer-promoting gene in some cancers." (PMID 37563232, 2023). "Then we detected the expression of HOTTIP and HOXA13 in clinical NPC patients and demonstrated the increased expression of HOTTIP and HOXA13 in cancer tissues, compared with those in paired normal tissues." (PMID 37392284, 2023). "HOXA13 can positively regulate the FAK/Src axis mediated by FN1 and transactivate ACLY and IGF1R to promote cancer progression." (PMID 37563232, 2023). "HOXA13, as a member of the homeobox (HOX) family, is involved in the regulation of cancer progression and has attracted increasing attention, as a potential novel target for anticancer strategies." (PMID 35197128, 2022). "HOXA13, HOXD13 and HOXC6 were reported to promote cancer progression in CRC, and HOXB13 was reported to suppress tumors in CRC." (PMID 34950145, 2021). "In CRC, HOXA13, HOXD13 and HOXC6 were reported to promote cancer progression, and HOXB13 was reported to suppress tumors." (PMID 34950145, 2021). "The results analysis demonstrated that both mRNA and protein level of HOXA13 were elevated in cancer tissues, compared with those in normal tissues." (PMID 37392284, 2023). "HOXA13, as a member of the HOX gene family, has been frequently researched in cancer progression." (PMID 35197128, 2022).
cancer (continued). "Although the entire HOX network plays a central role in cancer development and progression, the most posterior genes of the network, HOX13 paralogues (HOXA13, HOXB13, HOXC13 and HOXD13), specifically, are crucial in modulating these processes, in cooperation with co-localizing lncRNAs." (PMID 31137568, 2019). "Moreover, prior studies revealed oncogenic function of HOXA11, HOXA13, and HOXD11 in other cancers, implicating these genes in the pathogenesis of SEPN, although further studies will be needed to elucidate their role in this setting." (PMID 29383182, 2017). "Given that the physical distance between LNCRNA-HIT, HOXA13, and HOTTIP is only 6.5 kb in both humans and mice, it is possible that LNCRNA-HIT’s function may also be co-opted in these cancers." (PMID 26633036, 2015). "In addition, this research found that HOTTIP was positively correlated with HOXA13, and it was speculated that HOTTIP could play a cancer-promoting role in PC through HOXA13." (PMID 35565245, 2022). "However, whether HOXA13 exert a cancer-promoting effect in NPC through Snail or MMPs has not been reported." (PMID 37563232, 2023). "Moreover, our data will allow to further investigate the implication of candidate upstream regulators of hsa-miR-1249-3p/HOXA13 axis on epithelial cell functions, such as the long non-coding RNA MIF-AS1, whose regulatory activity on hsa-miR-1249-3p has been demonstrated in cancer cells." (PMID 38129477, 2023).
tumor (46 papers, 2015 to 2025). "A recent study reported that elevated HOXA13 expression was associated with histological grade, T stage, N stage, and tumor size in CRC tissues." (PMID 34075028, 2021). "The elevated HOXA13 expression was associated with worse tumor differentiation, distant metastasis, and higher AJCC stage." (PMID 34075028, 2021). "In ESCC patients treated with neoadjuvant chemotherapy, HOXA13 expression is associated with the worst tumor regression grade." (PMID 31137568, 2019). "In addition, high HOXA13 expression was also significantly associated with higher tumor grade and TNM stage as well as poor overall survival." (PMID 37627895, 2023). "In addition, HOXA13 expression was significantly associated with lymphatic metastasis, higher tumor stage, and higher tumor grade." (PMID 37627900, 2023). "In addition, our study found a strong association between HOXA13 protein expression and tumor grade." (PMID 37627895, 2023). "Similarly, lncRNA HOTTIP/HOXA13 expression was linked to tumor progression and therapeutic outcome in HCC patients." (PMID 36338699, 2022). "Similarly to MEOX2, at tumor scale, HOXA13 upregulation was associated with enhancement of focal adhesion mediated by integrins and reduction of MAPK pathway activation." (PMID 34885053, 2021). "MTT, colony formation and transwell assays and xenograft tumour models were used to investigate the effects of HOXA13 on NPC HNE1 cells in vitro and in vivo." (PMID 37563232, 2023). "Student’s ttest also showed a statistically significant difference in the expression level of HOTTIP and HOXA13 between tumor tissues and normal tissues." (PMID 37392284, 2023). "HOXA13 can also exhibit opposing oncogenic effects in the same type of tumour, depending on its cell characteristics." (PMID 37563232, 2023). "The overexpression of HOXA13 has been shown to promote tumor cell proliferation, migration, invasion, metastasis, and epithelial–mesenchymal transition, as well as inhibit apoptosis." (PMID 37627895, 2023). "Accordingly, hyperacetylation/upregulation of oncogenes related with angiogenesis and vascular invasion (COL24A1, NDP and HOXA13) and hypoacetylation/downregulation of angiogenesis-tumor suppressor genes (CD40 and IL15) was identified in this study." (PMID 35740301, 2022). "We generated a subcutaneous tumor model to assess the role of HOXA13 in 5-FU anti-tumor effect in vivo." (PMID 34094932, 2021). "Compared with shNC group, the tumor sizes of shHOXA13 group were more significantly inhibited by 5-FU, indicating that downregulation of HOXA13 expression improved the sensitivity of GC cells to 5-FU in vivo." (PMID 34094932, 2021). "The performed statistical analysis reveals for both HOXA13, HOXC13, HOXD13 a strong association with tumor grading classification." (PMID 34208964, 2021). "HOXA13 aberrant expression correlates with GC tumor stage, histological differentiation and survival of the patient." (PMID 31137568, 2019). "Studies have showed that Hoxa13 regulates tumor progression and embryonic limb formation through regulating cell apoptosis." (PMID 31165722, 2019). "HoxA13 is highly expressed in tumor cells of Gleason pattern 4 DACs, especially those surrounding papillary cores and comprising large ducts." (PMID 31882852, 2019). "Knockdown of HoxA13 expression induced by shHoxA13 lentivirus also significantly impaired tumor formation ability of CS12 cells in SCID mice." (PMID 27144338, 2016). "Hematoxylin and eosin staining of tumor sections demonstrated that tumor regions shrank by knockdown of HOXA13." (PMID 27144338, 2016). "In these tissues, Tgfβ should induce both LncRNA-HIT and Snd1 (p100) which would activate Hoxa13, which has been previously shown to mediate the formation of vascular tissues, providing a mechanism to promote tumor vascularization and growth." (PMID 26633036, 2015). "Recent studies demonstrated that HOXA13 was involved in carcinogenesis and the promotion of tumor growth." (PMID 26356815, 2015).
tumor (continued). "A heat map showed that the candidate genes involved in these four pathways were most significantly altered along increasing tumor grades with the up-regulation of HOXA13." (PMID 26356815, 2015). "Notably, high HOXA13 expression was significantly associated with NMIBC, lower tumor grade, higher number of lymph node metastases, and recurrence risk." (PMID 37627895, 2023). "In addition, we detected the mRNA and protein expression of Ki-67 in xenograft tumour tissues, and found that overexpression of HOXA13 increased the expression of Ki-67, while silencing induced the reverse effect (P < 0.05)." (PMID 37563232, 2023). "High HOXA13 expression was significantly associated with non-muscle invasive bladder cancer, lower tumor grade, higher number of lymph node metastases, and recurrence risk." (PMID 37627895, 2023). "This was not a surprise, as miR-128-3p has been indicated in previous studies to have a role in the inhibition of cell proliferation, but further investigation suggested that its target gene may be HOXA13, which contributes to the proliferation of tumor cells." (PMID 36290414, 2022). "In addition, its expression has been detected in HCC cell lines originating from liver stem-like cells, suggesting the HOXA13 role in the differentiation and tumor evolution of hepatic stem cells." (PMID 31137568, 2019). "In vivo, inhibition of HOXA13 inhibited tumor growth and prolonged animal survival." (PMID 26356815, 2015). "Similarly, hematoxylin and eosin staining of the brain tissues resected from the orthotopic mice showed that the Lenti-si HOXA13-treated tumor volume was reduced when compared to the Lenti-NC-treated tumors." (PMID 26356815, 2015). "We observed enhanced expression of HOXA13 levels both in tumor tissues and cell lines." (PMID 25889214, 2015). "Furthermore, downregulation of HOXA13 in orthotopic tumors decreased tumor growth." (PMID 26356815, 2015). "Transcription factor HOXA13 directly activates both System Xc− subunits (SLC7A11 and SLC3A2), and HOXA13 knockdown combined with ferroptosis inducers significantly suppresses tumor growth in vivo." (PMID 41462716, 2025). "Silencing HOXA13 suppressed the proliferation, migration, and invasion of HNE1 cells, which inhibited tumour growth, while overexpression of HOXA13 induced the opposite effects." (PMID 37563232, 2023). "It was worth noting that we found HOXA13 and HOXA3 were upregulated in tumor samples compared with normal samples." (PMID 35342423, 2022). "Mechanistically, YTHDC2 decreased homeobox A13 (HOXA13) mRNA stability by recognizing the m6A site in the 3′-UTR to suppress SLC3A2 expression, thereby inhibiting LUAD antioxidation and further limiting tumor progression." (PMID 35090469, 2022). "The result showed that the tumor volumes of MKN45-shHOXA13 group were smaller than those of shNC group, indicating knockdown of HOXA13 weakened tumorigenicity of MKN45 cells." (PMID 34094932, 2021). "In detail, HOXA13 always appears to be downregulated in the prognostically most unfavorable category, NECG3, compared to the other tumor types." (PMID 34208964, 2021). "HOXA7, HOXA10 and HOXA13, which are highly expressed in LSCC tissues, have a weak positive correlation with tumor purity." (PMID 33763449, 2020). "The knockdown of HOXA13 in ESCC cell model leads to a reduced number of colonies in vitro and tumor growth in nude mice." (PMID 31137568, 2019).